DLC1 (DLC1 Rho GTPase activating protein)
Diseases named in the same sentence as DLC1 in open-access papers (continued):
Sharing a sentence is not in itself a finding about the gene and the disease.
cancer (continued). "In 34 out of 81 HCC tissues, no DLC1 immunoreactivity was observed in the cytoplasm of the cancer cells." (PMID 25013499, 2014). "Deleted in liver cancer 1 (DLC1), a GTPase-activating protein (GAP) domain containing tumor suppressor which localizes at focal adhesions, is considered as a potential tumor suppressor for many malignant tumors." (PMID 23988121, 2013). "Altogether, our findings unravel a tight and multilayered regulation of DLC1/Rho/ROCK signaling by EZH2, which may underpin a critical epigenetic driven event in promoting cancer metastasis." (PMID 23826380, 2013). "Consistent with the findings from human HCC, concomitant DLC1 down-regulation and EZH2 up-regulation was observed in these malignancies, suggesting the implications of EZH2 up-regulation in silencing DLC1 expression in different human cancers." (PMID 23826380, 2013). "Treating cancer cells with the EZH2 small molecular inhibitor, 3-Deazaneplanocin A (DZNep), restored DLC1 expression in different cancer cell lines, indicating that EZH2-mediated H3K27me3 epigenetic regulation of DLC1 was a common mechanism in human cancers." (PMID 23826380, 2013). "However, in our studies DLC1 reconstitution failed to completely rescue the effects of chr8pLOH on cancer cell migration, similar to the other metastasis suppressor candidates indicating cooperating roles of these genes in suppressing invasiveness." (PMID 38134284, 2023). "Furthermore, DLC1 could induce apoptosis, senescence and autophagy of cancer cells by regulating the EGFR/Akt/ NF-κB signalling pathway, and suppress the proliferation and migration of tumors by modulating DLC1/RhoA pathway." (PMID 37737712, 2023). "Thus, we propose opposing regulatory mechanisms of DLC1 protein homeostasis by USP7 and HECTD1, which could open up strategies to counteract downregulation and restore DLC1 expression in cancer." (PMID 35322810, 2022). "DLC1 was consistently downregulated or absent in various malignant tumors, including CRC." (PMID 36185184, 2022). "Therefore, we suggest that a combination of miR-200c-3p and the molecular target sites of DLC1 could be a potential regulator in HGSC for therapeutic purposes and to reverse cancer progression in this deadly disease." (PMID 34071861, 2021). "DLC-1 and DLC-2 are frequently down-regulated, as opposed to mutated, in cancer." (PMID 33142932, 2020). "However, this hypothesis has never been tested experimentally and the mechanistic basis of how DLC1 suppresses cancer cell metastasis has not been delineated." (PMID 18648664, 2008). "In addition to reporting that DLC1 protein is a new critical substrate for cytoplasmic EZH2, this study provides a rational approach for combination molecular targeted agent cancer treatment by non-genetically reactivating a tumor suppressor protein, leading to potent antitumor activity." (PMID 34862367, 2021).
hematologic malignancies (2 papers, 2012). "Indeed, highly recurrent alterations of DLC1 have been found in solid tumors and hematologic malignancies, and a meta-analysis of microarray experiments lists DLC1 as the fifth of the top-50 genes implicated in multiple cancers." (PMID 22580498, 2012). "DLC1 (deleted in liver cancer 1), a tumor suppressor gene that encodes a RhoGTPase-activating protein, is recurrently downregulated or silenced in various solid tumors and hematological malignancies because of epigenetic modifications or genomic deletion." (PMID 23285118, 2012).
infection (2 papers, 2013 to 2022). The state of being infected such as from the introduction of a foreign agent such as serum, vaccine, antigenic substance or organism. "Infection of AGS/Cav1 cells triggered the recruitment of p120 RhoGTPase-activating protein/deleted in liver cancer-1 (p120RhoGAP/DLC1) to Cav1 and counteracted CagA-induced cytoskeletal rearrangements." (PMID 23592983, 2013). "To date, DLC1 has not been functionally connected with H. pylori in patients or animal models, although gene hypermethylation was detected upon infection." (PMID 35963849, 2022). "After dichotomous grouping as negative (scores 0/1) vs. positive (scores 2/3) cases, DLC1 staining was correlated to the infection status (n = 9–10 per group)." (PMID 35963849, 2022).
DLC1 also shares sentences with these, for which no sentence is quoted: lung squamous cell carcinoma (4 papers); invasive breast carcinoma (3); bladder urothelial carcinoma (2); renal cell carcinoma (2); acute myeloid leukemia (1); adenocarcinoma (1); anencephaly (1); cervical adenocarcinoma (1); cervical squamous cell carcinoma (1); cholangiocarcinoma (1); chordoma (1); Cirrhosis (1); clear cell renal cell carcinoma (1); colorectal (1); cutaneous squamous cell carcinoma (1); endocervical adenocarcinoma (1); esophageal cancer (1); genetic disorders (1); H. pylori (1); head and neck tumours (1); heart disease (1); hereditary colorectal cancers (1); hereditary hemochromatosis (1); Hodgkins lymphoma (1); Insulin resistance (1); lentivirus infection (1); liver neoplasms (1); Lynch syndrome (1); metabolic disease (1); metastasis (1).
A further 11 diseases each share a sentence with DLC1 in 1 paper.